DGAT2L6 (diacylglycerol O-acyltransferase 2 like 6)
Description:
Diglyceride acyltransferase that uses fatty acyl-CoA as substrate. Particularly active with oleate as a substrate. Has no wax synthase activity to produce wax esters. Able to use 1-monoalkylglycerol (1-MAkG) as an acyl acceptor for the synthesis of monoalkyl-monoacylglycerol (MAMAG).
Synonyms: DC3; FLJ25989
Tractability: Antibody: UniProt predicts a signal peptide or a membrane-spanning region.
Target class: Enzyme; Transferase
Gene: Protein-coding gene on chromosome X (70,177,483 to 70,205,704, forward strand). Ensembl gene ENSG00000184210.
Subcellular location: Endoplasmic reticulum membrane
Pathways (Reactome):
Metabolism: Acyl chain remodeling of DAG and TAG
Gene Ontology:
Molecular function: diacylglycerol O-acyltransferase activity; protein binding; acyltransferase activity, transferring groups other than amino-acyl groups
Biological process: monoacylglycerol biosynthetic process; acylglycerol acyl-chain remodeling
Cellular component: endoplasmic reticulum membrane
Homologues: Orthologues: chimpanzee DGAT2L6 (99% identical), macaque DGAT2L6 (93% identical), guinea pig DGAT2L6 (81% identical), rat Dgat2l6 (77% identical), pig DGAT2L6 (77% identical), rabbit DGAT2L6 (75% identical), mouse Dgat2l6 (72% identical), Caenorhabditis elegans K07B1.4 (41% identical), Caenorhabditis elegans Y53G8B.2 (40% identical), Drosophila melanogaster CG1941 (38% identical), Caenorhabditis elegans dgtr-1 (38% identical), Drosophila melanogaster Dgat2 (38% identical), and 2 more. Paralogues in human: DGAT2 (51% identical), AWAT1 (51% identical), AWAT2 (51% identical), MOGAT3 (45% identical), MOGAT1 (44% identical), MOGAT2 (43% identical).
Diseases named in the same sentence as DGAT2L6 in open-access papers:
DGAT2L6 is named in the same sentence as 1 disease in open-access papers, as found by Europe PMC text mining. Sharing a sentence is not in itself a finding about the gene and the disease.
DGAT2L6 shares sentences with these, for which no sentence is quoted: tumor (1 paper).